STAT3 (signal transducer and activator of transcription 3)
Diseases named in the same sentence as STAT3 in open-access papers (continued):
Sharing a sentence is not in itself a finding about the gene and the disease.
T-LGL leukemia (continued). "By using TL1, a human T-LGL cell line, we could show that miR-181a is an actor in T-LGL leukemia, driving STAT3 activation by SOCS3 inhibition and ERK1/2 phosphorylation by DUSP6 inhibition and verified this mechanism in an independent cell line." (PMID 34873301, 2022). "Activating point mutations in STAT3 are not pathognomonic for T-LGL leukemia and can be detected in various hematological and non-hematological malignancies." (PMID 36117975, 2022). "There are a couple key differences to note between STAT3 and STAT5b mediated LGL leukemia." (PMID 36755813, 2022). "On the other hand, T-LGL leukemia cases without STAT3 mutations are still associated with increased STAT3 signaling." (PMID 35270020, 2022). "STAT3 mutations were detected by NGS in peripheral blood, bone marrow, and spleen in a total of 56% of patients in our cohort, providing an argument for considering these cases as atypical aleukemic presentation of T-LGL leukemia." (PMID 36117975, 2022). "Interestingly, in contrast to patients with FS, LGL leukemia/RA patients exhibited increased LGL counts >2 x 10e9/L (21% vs. 0% in FS) and STAT3 mutations (39% vs. 0% in FS)." (PMID 35646651, 2022). "Nevertheless, the significance of STAT3 mutations in distinguishing T-LGL leukemia from TCUS is not clear." (PMID 36117975, 2022). "This may indicate that while levels of C24:0-SM may be lower in LGL leukemia, this particular SM may still be associated with LGL leukemic survival through its correlation with mutant STAT3." (PMID 36361536, 2022). "Mutations in STAT3 and (to a lesser extent) STAT5 have been evaluated to be frequently leukemogenic in adults with large granular lymphocyte leukemia, and activating somatic STAT3 mutations have been found in T and B cell lymphomas and chronic lymphoproliferative disorders of NK cells." (PMID 33672930, 2021). "Overall, these data suggest that MCV, a parameter of red blood cell size not previously well‐studied in LGL leukemia, correlates with D661 mutations in STAT3." (PMID 32710512, 2020). "Activating mutations of JAK1-3 and STAT3-5 have also been found in a subset of NK/T-cell lymphomas, non-hepatosplenic gamma-delta T-cell lymphoma, large granular lymphocytic leukemia and T-cell prolymphocytic leukemia." (PMID 32188095, 2020). "A recent clinical investigation has shown the JAK1/JAK3 inhibitor tofacitinib to be a promising salvage therapy for refractory T-LGL leukemia patients with or without STAT3 mutations." (PMID 29228628, 2017). "Consistently, when we triggered STAT3 phosphorylation with IL-6 (20 ng/ml) or IL-15 (20 ng/ml), key cytokines in LGL leukemia development, after one hour culture we observed an increase of Fas ligand transcription levels (1.59- and 2.01-fold after IL-6 and IL-15, respectively)." (PMID 28977911, 2017). "Thus STAT3 can be served as an auxiliary diagnosis tool of classifying LGL leukemia as true T-cell leukemia or hyperreactive or persistent T-cell response." (PMID 28427176, 2017). "Furthermore, CK2 inhibition diminished the Jak1- and Src kinase-dependent phosphorylation of a constitutively active STAT3 mutant recently described in human large granular lymphocytic leukemia." (PMID 24742922, 2014). "It has been suggested that STAT3 mutations may not be the initial trigger of the leukemic process in LGL leukemia." (PMID 38611065, 2024). "However, considering the high levels of S1P and STAT3 in these patients, perhaps high STAT3, even if not mutated, contributes to the pathogenesis of T-LGL leukemia." (PMID 36361536, 2022). "Interestingly, T-LGL leukemia patients with STAT3 mutations are more likely to have RA than those without." (PMID 35646651, 2022). "As to the biological effect of the mutations, we detected a modest but statistically significant decrease in neutrophils in the MS patients with mutations vs. non-carriers, consistent with reports of neutropenia in STAT3 mutation related T-LGL leukemia and Felty syndrome." (PMID 36441748, 2022).
T-LGL leukemia (continued). "Sex distinctions according to STAT3 mutation subtypes were not made in any of these publications, but our work indicates that this could be another factor to consider when analyzing LGL leukemia patient clinical features." (PMID 32710512, 2020). "Clinically, patients with large granular lymphocyte leukemias tended to have significantly smaller cells if their cells demonstrated STAT3 mutations in the SH2 domain compared to patients whose cells did not have STAT3 mutations." (PMID 30116531, 2018). "Constitutive activation of STAT3 and production of IL6 induce an increase in the transcription and expression of Fas ligand in LGL leukemia." (PMID 35178350, 2022). "We identified that the overexpression of one particular miRNA, miR-181a, which results in hyperactive STAT3 and ERK1/2 by decreasing SOCS3 and DUSP6 expression in T-LGL leukemia patient cells, eventually leads to resistance to FAS-mediated apoptosis." (PMID 34873301, 2022). "Notably, T-cell clonality and STAT3 mutations were detected more frequently in spleen samples than peripheral blood or bone marrow from ten atypical LGL leukemia/RA patients with lymphopenia, severe neutropenia, and marked splenomegaly, emphasizing the potential for LGL leukemia misdiagnosis as FS." (PMID 35646651, 2022). "Soluble Fas-L (sFas-L), increased in the sera of LGL leukemia patients, especially those with CD8+CD16+CD56− LGLs and STAT3 hyperactivation, functions as a decoy receptor preventing Fas-mediated apoptosis." (PMID 34572739, 2021). "Next, a heatmap was generated to visualize the LGL leukemia patients and normal donors in columns labeled with ANC, Hgb, MCV, STAT3 status, LGL leukemia subtype, and sex." (PMID 32710512, 2020). "This might suggest that STAT3 and STAT5b are less clearly implicated in the pathogenesis of TCRγδ+ T-LGL leukemia than CD8+TCRαβ+ T-LGL and/or NK-LGL leukemia." (PMID 28407008, 2017). "EMSA experiments later showed that STAT3 can directly bind these STAT3 elements within the MCL1 promoter and drive gene activation in LGL leukemia cells." (PMID 24743777, 2014). "Dysregulated STAT1, STAT3, and STAT5 signaling is well documented in LGL leukemia." (PMID 31947841, 2020). "Two sphingomyelins (SMC24 and SMC26:1) showed positive and linear relationships with WT and mutant STAT3, respectively, but the role of these sphingolipids in LGL leukemia is not known." (PMID 32710512, 2020). "Both of these cases had somatic gain-of-function mutations in STAT3; however, this was not confined to one clonal subpopulation or found in all the clonally expanded CD8+ cells as seen in classic T-LGL leukemia." (PMID 29963054, 2018). "The finding of an miR-181a-SOCS3-pSTAT3 axis in T-LGL leukemia is of broader importance, as it could potentially clarify why STAT3 nonmutated patients also acquire hyper-activation of the STAT3 molecule." (PMID 34873301, 2022). "One is that CD4+ T-LGL leukemia is characterized only by STAT5B mutations and not STAT3 mutations." (PMID 36755813, 2022). "Therefore, we hypothesize here that miRNAs might be involved in the regulation of key molecules such as STAT3 and ERK1/2 in T-LGL leukemia." (PMID 34873301, 2022). "To confirm the findings and study STAT3 activation in other T cell malignancies, we measured STAT3 and pY-STAT3 levels by Western blotting in ALCL, acute T-lymphoblastic leukemia (T-ALL), NK/T-cell lymphoma (NKT), T-cell large granular lymphocyte leukemia (T-LGL), and PTCL cell lines." (PMID 32188095, 2020). "However, the contribution of STAT3 to T-ALL leukemogenesis is debatable, because no recurrent STAT3 mutations have been found in patients with T-ALL, and it is more associated with mature T cell cancers, such as T cell large granular lymphocytic leukemia or NK cell or NK/T cell leukemia." (PMID 38618957, 2024). "Notably, the STAT3 pathway is dysregulated as well, in particular through the inhibition of SOCS3, a protein that is absent in all T-LGL leukemia cells." (PMID 34873301, 2022).
oral squamous cell carcinoma (78 papers, 2002 to 2025). "For example, in oral squamous cell carcinoma, depending on whether exon 23 is missing, STAT3 produces two variants by alternative splicing." (PMID 33976726, 2021). "Retraction of: Huang J, Lv C, Zhao B, Ji Z, Gao Z. SCARA5 inhibits oral squamous cell carcinoma via inactivating the STAT3 and PI3K/AKT signaling pathways." (PMID 41141927, 2025). "STAT3 has proliferative and anti-apoptotic effects that play a role in inflammation and resistance to anti-cancer therapies, even in oral squamous-cell carcinoma." (PMID 41190326, 2025). "STAT3 activation plays a pivotal role in the progression and maintenance of oral squamous cell carcinoma (OSCC), primarily by enhancing tumor cell survival, immune evasion, and drug resistance." (PMID 40140827, 2025). "JAK2/STAT3 is a well‐known oncogenic pathway that leads to a variety of solid malignancies, including oral squamous cell carcinoma." (PMID 36708238, 2023). "Mechanistically, silencing of KRT16 induced protein degradation of β5-integrin and c-Met, contributing to blockage of the downstream Src/STAT3/FAK/ERK signaling in oral squamous cell carcinoma cells." (PMID 35037835, 2022). "ALDH3A1 acts as a prognostic biomarker and inhibits the epithelial–mesenchymal transition of oral squamous cell carcinoma through IL-6/STAT3 signaling pathway." (PMID 34928471, 2022). "STAT3 plays a variety of biological effects in the degree of invasion, lymph node metastasis, and different clinical grades of oral squamous cell carcinoma." (PMID 36092922, 2022). "CCL18/PITPNM3 axis also activates JAK2/STAT3 signaling pathway to promote the growth and metastasis of oral squamous cell carcinoma cells." (PMID 35609322, 2022). "The aberrant activation of JAK/STAT signaling and its association with constitutively expressed p-STAT3 at tyrosine/serine and total STAT3, Erk1/2, and cyclin D1 has been observed in oral squamous cell carcinoma (OSCC) cell lines." (PMID 35401182, 2022). "We previously reported that the promoter region of the human ITGB6 gene contains STAT3 binding sites, and the basal rate of ITGB6 expression in oral squamous cell carcinoma cells is primarily defined by STAT3." (PMID 36299623, 2022). "For example, CCR7 and its ligand chemokine ligand 21 (CCL21) promote the EMT and up-regulate the stemness of oral squamous cell carcinoma by activating the JAK2/STAT3 signaling pathway." (PMID 35538537, 2022). "A significant association of smokeless tobacco consumption habits and accumulation of nuclear p-STAT3 was observed in clinical oral squamous cell carcinoma tissues." (PMID 35401182, 2022). "According to the work of Cui and coworkers, downregulation of PD-L1 with siRNA led to a decreased phosphorylation of ERK and STAT3 in oral squamous cell carcinoma cell lines." (PMID 34185141, 2021). "An earlier study revealed that FZD2 promotes cell motility and invasiveness in oral squamous cell carcinoma cells via the regulation of the STAT3 pathway." (PMID 31595151, 2019). "We found a negative correlation between the expression of hsa-miR-21 expression and STAT3 in oral squamous cell carcinoma." (PMID 29976158, 2018). "In the present study, we examined the effect of a novel small-molecule microtubule inhibitor, MPT0B098, on STAT3 signaling in oral squamous cell carcinoma (OSCC)." (PMID 27367272, 2016). "Using confocal microscopy, we confirmed IL-22-induces P-STAT3 nuclear accumulation and STAT3 nuclear translocation, as recently described in oral squamous cell carcinoma." (PMID 25793261, 2015). "We examined the expression of STAT3 and miR-21 in 43 oral squamous cell carcinoma (OSCC) tumors and classified them into cisplatin sensitive or resistant group." (PMID 25514838, 2014). "We recently showed that treatment with 15d-PGJ2 induces apoptosis accompanied by downregulation of the oncogenic signal transducer and activator of transcription 3 (Stat3) signalling in human oral squamous cell carcinoma (SCC) cells." (PMID 15316561, 2004).
oral squamous cell carcinoma (continued). "P. gingivalis also appears to stimulate IL-6 expression via the janus kinase 2/glycogen synthase kinase 3 beta/signal transducer and activator of transcription 3 (JAK2/GSK3-β/STAT3) signaling pathway, which is linked to carcinogenesis and the development of oral squamous cell carcinoma." (PMID 40806122, 2025). "Regarding miR-20a-3p, evidence indicates that it functions as a tumor suppressor in oral squamous cell carcinoma because it reduces the migration and proliferation of a cell model, inhibiting STAT3 (Signal Transducer And Activator Of Transcription 3) expression." (PMID 40869968, 2025). "Similarly, FZD2 has been shown to promote migration and invasion in oral squamous cell carcinoma (OSCC) through the STAT3 pathway." (PMID 40444048, 2025). "Interestingly, CCL4 has been found to promote p-MEK, p-ERK1/2, and p-STAT3 activation, leading to increased angiopoietin 2 expression, thereby facilitating angiogenesis in oral squamous cell carcinoma." (PMID 38739303, 2024). "In addition, PLOD2 activated integrin β1 through IL-6/STAT3 signaling to promote invasion and metastasis in oral squamous cell carcinoma." (PMID 38184566, 2024). "STAT3 has been reported to be involved in radiosensitivity of oral squamous cell carcinoma." (PMID 36092922, 2022). "So we believe that neutrophils may promote tumor progression (proliferation and invasion) via regulating EMT and JAK2/STAT3 signaling through Chemerin in Oral squamous cell carcinoma." (PMID 35155249, 2022). "Similarly, honokiol also induces apoptosis through the suppression of JAK2/STAT3, Akt and Erk signalling pathways in human oral squamous cell carcinoma (SAS and OCEM-1) cell lines." (PMID 31877856, 2019). "The STAT family member STAT3 has been reported to possess oncogenic potential as constitutive activation in oral squamous cell carcinoma (OSCC) and transduce signals elicited by various cytokines leading to regulation of specific target genes that contribute to a malignant phenotype." (PMID 27367272, 2016). "Our results provide the first evidence of significant antineoplastic effects of 15-PGJ2 on human oral squamous cell carcinoma cells, which may be related to downmodulation of Stat3 and are at least partly mediated through PPARγ-independent events." (PMID 12454768, 2002). "Additionally, P. gingivalis seems to promote IL-6 expression through the janus kinase 2/glycogen synthase kinase 3 beta/signal transducer and activator of transcription 3 (JAK2/GSK3-β/STAT3) pathway, which is associated with carcinogenesis and oral squamous cell carcinoma." (PMID 40805993, 2025). "IL-6 could promote proliferation via JAK2/STAT3/SOX4 pathway in oral squamous cell carcinoma cells." (PMID 39963655, 2024). "Therefore, this study mainly explored the expression of CircPUM1 and mir-580/STAT3 in oral squamous cell carcinoma and analyzed whether CircPUM1 regulates radiosensitivity through mir-580/STAT3." (PMID 36092922, 2022). "For example, in oral squamous cell carcinoma, the CCL21/CCR7 axis activates the JAK2/STAT3 signaling pathway to regulate the progression of EMT and promote the stemness of oral squamous cell carcinoma." (PMID 33788424, 2021). "A CC chemokine receptor 7 (CCR7) and CCL21 are abundant in oral squamous cell carcinoma (OSCC) tissues, where they regulate EMT process and promote OSCC desiccation through activation of the JAK2/STAT3 signaling pathway." (PMID 34421979, 2021). "Combination of STAT3 inhibitor and DDP treatment led to a notable reduction of STAT3/miR-21 axis and an increase of PTEN level, repressing oral squamous cell carcinoma (OSCC) cell proliferation, migration and invasion." (PMID 30217221, 2018). "STAT3 was hyper-phosphorylated in human oral squamous cell carcinoma (OSCC) compared with normal oral mucosa (NOM) and dephosphorylation of STAT3 by the potent STAT3 inhibitor, cryptotanshinone or NC decreased cell viability and induced apoptosis." (PMID 29207645, 2017).
oral squamous cell carcinoma (continued). "Using chromatin immunoprecipitation assays, this study has demonstrated, for the first time, that transcription factors STAT3 and C/EBPα are involved in the positive regulation of ITGB6 transcription in oral squamous cell carcinoma cells." (PMID 25816241, 2015). "Treatment of oral squamous cell carcinoma cells with 15-PGJ2 induced an initial reduction and eventual elimination of both phosphorylated and unphosphorylated Stat3 protein levels." (PMID 12454768, 2002). "In addition, pSTAT3 expression is significantly high in oral squamous cell carcinoma (OSCC), and STAT3 knockdown significantly inhibited migration, invasion, and epithelial-mesenchymal transition (EMT) in OSCC." (PMID 35090515, 2022). "In oral squamous cell carcinoma cell lines, PD-L1 is regulated by ERK and STAT3 signaling." (PMID 34185141, 2021). "A study reported another mechanism that IL-6/STAT3 pathway could be activated through ALDH3A1, contributing to reduced cell proliferation, migration, and invasion in oral squamous cell carcinoma 28, which was in consistent with our findings." (PMID 34234849, 2021). "In addition, oral squamous cell carcinoma (OSCC) stem cell-derived EVs contain miR-21-5p, which activates the phosphoinositide 3-kinase (PI3K)-mTOR-signal transducer and activator of transcription 3 (STAT3) signaling pathway in OSCC cells, leading to cisplatin resistance in non-OSCC stem cells." (PMID 40182121, 2025). "In oral squamous cell carcinoma cells, it was shown that in the absence of ERK1/2 signaling, there was a decrease in phosphorylated -serine STAT3, but an increase in phosphorylated -tyrosine STAT358." (PMID 30385793, 2018).